CXCR2 (C-X-C motif chemokine receptor 2)
Diseases named in the same sentence as CXCR2 in open-access papers (continued):
Sharing a sentence is not in itself a finding about the gene and the disease.
cancer (continued). "Prominent associations of CXCR2 with immune checkpoints, neoantigens, TMB, and MSI were observed in human cancers." (PMID 34840630, 2021). "IL-17 is proclaimed to increase CXCL5 expression of cancer cell, and subsequently enhancing the infiltration of MDSC into the cancer cell cluster in a CXCL5/CXCR2-dependent manner." (PMID 34689842, 2021). "It is suggested that selected chemokines such as CXCL8 and its specific receptor CXCR2 are involved in cancer progression, including GC." (PMID 34680333, 2021). "In particular, therapeutic blockade of CCL5-CXCR2 interaction by disrupting production of CCL5 or CXCR2 antagonist has demonstrated promising antitumor efficacies in several preclinical cancer models." (PMID 35003065, 2021). "The CXCR2–CXCLs axis is a crucial chemotactic factor for the recruitment of immune suppressive myeloid cells to lesions in various inflammatory diseases and cancer." (PMID 34575965, 2021). "CXCR2 is a well-studied player in the establishment in the metastatic niche in a variety of cancers." (PMID 34944914, 2021). "Mounting evidence supports the important role of CXCR2 in tumorigenesis and cancer patients’ prognosis." (PMID 33814009, 2021). "Neutrophils overexpressing CXCR2 are attracted to cancer-prone tissues via the cytokine IL-8 and chemokine ligands CXCL1, CXCL2 and CXCL5." (PMID 34674757, 2021). "Neutralisation of CXCR2 has shown promising results in various preclinical cancer models, usually as part of combined therapies to circumvent chemotherapy resistance." (PMID 34575965, 2021). "In this study, we have shown that PC has potential to induce necroptosis, and CXCL5 released from necroptotic cells promotes cancer cell migration and invasion via CXCR2 in PC cells." (PMID 31999765, 2020). "In in vivo cancer models, the inhibition of CXCR2 reduces neutrophil recruitment to tumors and increases the efficacy of chemotherapy." (PMID 32121107, 2020). "CXCR2, a G-protein-coupled receptor, and its ligand IL-8 are the most activated cytokine/chemokine in cancer and inflammation." (PMID 33184397, 2020). "Particularly, CXCR2 and CXCR4 are chemokine receptors for T-cells implicated in cancer invasion and metastasis." (PMID 32719800, 2020). "Huang and colleagues demonstrated that the possible pathogenic flora of colitis-related cancer was connected with the C-X-C motif receptor 2 (CXCR2) signaling axis during cancer progression." (PMID 33050883, 2020). "Next, we examined the involvement of CXCR2 in the process of necroptosis that promotes cancer cell migration and invasion." (PMID 31999765, 2020). "In conclusion, we have shown that key mediators of necroptosis were expressed in PC, and CXCL5 released from necroptotic cells promotes cancer cell migration and invasion via CXCR2 in PC cells." (PMID 31999765, 2020). "This confirmed a primary role of CXCR1/CXCR2 and their ligands in the recruitment of neutrophils from blood, in agreement with other cancer types." (PMID 32664318, 2020). "Inhibition of CXCR2 using SB225002 impeded cancer cell migration and invasion enhanced by necroptosis." (PMID 31999765, 2020). "Together, these findings propose CXCR2 as a suitable target to alleviate myeloid cell-induced immune suppression for a better therapeutic outcome in cancer patients." (PMID 32509781, 2020). "Here, in line with previous studies, we suggest the use of CXCR2 inhibition in combination with conventional chemotherapy or immunotherapy to reduce cancer-cell dissemination and improve therapy outcome." (PMID 32581213, 2020). "Recently, we demonstrated that the MDSC in premetastatic organ secreted the proinflammatory chemokine, chemokine (C-X-C motif) ligand 2 (CXCL2) to attract C-X-C motif chemokine receptor 2 (CXCR2)-expressing cancer cells." (PMID 32170086, 2020).
cancer (continued). "In this study, we further discovered that PDAC and cancer-associated fibroblast (CAF) accelerated each other’s invasion and migration through the CXC chemokines-receptor (CXCLs–CXCR2) axis." (PMID 30659170, 2019). "Both the cancer cells and additional marrow cells expressed CXCR2 protein, including bone cells with the pathology of osteocytes and chondrocytes." (PMID 31562303, 2019). "Cancer cell proliferation significantly decreased compared to controls after antCXCR2 addition, suggesting that CXCR2 is necessary to induce proliferation in the IC-primed bone cultures (right)." (PMID 31562303, 2019). "The binding of CXCL8 to CXCR2 in cancer cells facilitates metastasis, which was also observed in MDA-MB-231 cells and xenograft mouse models with CXCR2-knockout, as well as decreased migration, compared with wild-type cells." (PMID 31788042, 2019). "There are now over 2,400 publications describing a role for CXCR4 in cancer and over 300 publications describing a role for CXCR2 in cancer progression." (PMID 30873179, 2019). "IL-8 and its receptors, CXCR1 and CXCR2, have been extensively reported to mediate invasion, angiogenesis, and metastasis of various cancers." (PMID 31684995, 2019). "Our results demonstrate that CXCL5 is sufficient to induce cancer cell proliferation in bone cultures and that blocking CXCR2 with an antagonist inhibits proliferation of cancer cells and prevents CXCL5-induced signaling." (PMID 31562303, 2019). "The chemokines (CXCL1, 2, 5, and 8) upregulated by cancer-derived VEGF-C in LECs are all cognate ligands of CXCR2." (PMID 31390756, 2019). "It has been reported that the AKT, ERK, JNK, and STAT3 pathways were related to the evolution and progression of carcinoma mediated by the CXCL5/CXCR2 axis." (PMID 30792394, 2019). "Quite a few studies had investigated the correlation between CXC chemokine receptor 2 (CXCR2) and cancer." (PMID 29599927, 2018). "There are additional supportive data, generated primarily from the cancer and autoimmunity literature, that establishes a role for CXCR2-mediated trafficking and activation in PMN-MDSC-mediated pathology." (PMID 30081463, 2018). "This meta-analysis was aimed to comprehensively summarize the previous studies and to explore the prognostic value of CXCR2 in patients with cancer." (PMID 29599927, 2018). "Overall, according to the result of our meta-analysis, the better clinical management of cancer will be taken with the help of CXCR2 in the future." (PMID 29599927, 2018). "The result that high-level of CXCR2 was a risk factor of both OS and PFS, consistent with previous finding, strengthened the fact that low expression of CXCR2 predicted better efficacy of cancer therapy." (PMID 29599927, 2018). "In this meta-analysis, it was first synthetically declared that CXCR2 was a potential and potent prognosis predictor in patients with cancer except for digestive tract cancer with wide application in clinic." (PMID 29599927, 2018). "Additional high-quality clinical research data and larger sample sizes are needed to characterize the role of CXCR2 expression in cancer further." (PMID 29312644, 2017). "IL-8 mediates its biological effects through two cell-surface G protein-coupled receptors, termed CXCR1 and CXCR2, found on cancers cells, endothelial cells, neutrophils, and TAMs." (PMID 28545495, 2017). "The patients who were positive for both CXCL1 in cancer cells and CXCR2 in stromal cells (n = 74) had significantly worst prognoses in comparison with the other groups." (PMID 28575019, 2017). "Previous studies have shown that CXCR2 can be activated by CXCL5 or other ligands to stimulate cancer progression through the activation of downstream pathways, such as JAK/STAT3, JNK, PI3K/AKT and ERK1/2 pathway." (PMID 28356111, 2017).
cancer (continued). "In the present study, the Kaplan-Meier survival curves for the patients revealed that those with CXCL1 expression in cancer cells and those with CXCR2 expression in stromal cells had poorer survival rates than the patients without either of these expressions." (PMID 28575019, 2017). "It was reported that the chemokine (C-X-C motif) ligand 1 (CXCL1) from cancer cells stimulated the recruitment of bone marrow-derived mesenchymal cells (BM-MCs) into tumor stroma via chemokine (C-X-C motif) receptor 2 (CXCR2) signaling." (PMID 28575019, 2017). "CXCR2 is an essential regulator of neutrophil recruitment to inflamed and damaged sites and plays prominent roles in inflammatory pathologies and cancer." (PMID 28205614, 2017). "On the other hand, the protein expression of both CXCL1 in cancer cells and CXCR2 in stromal cells was significantly correlated with overall survival." (PMID 28575019, 2017). "This is the first report that demonstrates clinical significance CXCL1 expression of cancer cells and CXCR2 expression of fibroblasts." (PMID 28575019, 2017). "The interactions between CXCR2+ neutrophils and cancer cells enhance the expression of their metastatic genes, thus activating this cancer-spreading mechanism." (PMID 28473858, 2017). "Accordingly, small molecule antagonists of CXCR2 are being actively tested for potential anti-cancer effects in vivo." (PMID 28205614, 2017). "It was reported in many studies that miR-940 was highly expressed in normal tissues compared with tumors, and miR-940 was shown to inhibit the migratory and invasive potential of cancer cells by suppressing CXCR2, MIEN1, MyD88, Nestin, and ZNF24." (PMID 28423620, 2017). "Elevated levels of CXCL1 and CXCR2 positively correlate with the poorer prognosis of cancer patients." (PMID 27446967, 2016). "The significance of murine functional homologs of IL-8 and CXCR2 in mediating MDSC homing in cancer, however, has been described." (PMID 27348007, 2016). "CXCR2 has previously been shown to increase cell proliferation, cancer angiogenesis, and promote the resistance of cancer cells to conventional treatment." (PMID 27028996, 2016). "Experimental results reveal that IL-8 upregulates CXCR1 and CXCR2 expression, suggesting that the cancer progression of HNSCC cells that is induced by IL-8 depends on both CXCR1/2 receptors." (PMID 27557518, 2016). "The migratory capacities of SK-OV3 cells were assessed with a scratch assay and the potential role of CXCR2 in mediating the effects of volatile anaesthetics on cancer cell biology were further investigated with CXCR2 knockdown by siRNA." (PMID 27028996, 2016). "Based on the correlation between CXCR2 expression and the effects of volatile anaesthetics on cancer cells we carried out further investigations to evaluate the knock-down effect of CXCR2 on the migratory activity of SKOV3 cells." (PMID 27028996, 2016). "This study also showed that IL-8 in vitro attracted CXCR1- and CXCR2-expressing MDSCs isolated from cancer patient peripheral blood mononuclear cells, and that IL-8 induced extrusion of neutrophil extracellular traps from MDSCs with a granulocytic phenotype." (PMID 27348007, 2016). "It is well known that CXCR2 participates in chronic inflammation, angiogenesis, tumorigenesis and metastasis in several types of carcinomas by binding to its native ligand interleukin-8 (IL-8)." (PMID 27556695, 2016). "CXCR2 is well known for playing critical roles in cancer progression by modulating the cell cycle, apoptosis, and angiogenesis." (PMID 25944970, 2015). "Several small molecule CXCR2 inhibitors with appropriate in vivo pharmacokinetic properties are currently in preclinical and clinical development for the treatment of cancer and inflammatory diseases." (PMID 26414070, 2015). "According to the results of IHC, CXCR2 expression was observed mainly in the cell wall of the cancer cells, and 33 of the 82 cases (40.2 %) were evaluated as CXCR2-positive." (PMID 26231560, 2015).
cancer (continued). "IL-8 confers its effects on cellular phenotypes upon binding to its two cell surface cognate receptors, CXCR1 and CXCR2, which are widely expressed on the cancer as well as endothelial cells." (PMID 25970774, 2015). "CXCR2, an interleukin-8 receptor, is reportedly expressed in several carcinomas, and interleukin-8 signaling promotes cancer cell proliferation." (PMID 26231560, 2015). "ELR-CXC chemokines stimulate a wide array of downstream signaling molecules through binding to CXCR1 and CXCR2, among which activation of MAPK and AKT is closely implicated in cancer development and progression." (PMID 26087179, 2015). "All ELR+ CXC chemokine ligands, binding to CXCR2, mediated angiogenic activity, which was crucial for cancer cells proliferation." (PMID 26497045, 2015). "Activated CXCR2 was found to promote cell proliferation, migration, and invasion and to assist cancer cells in evading stress-induced apoptosis." (PMID 25011526, 2014). "Third, inhibition of signaling by CXCR2, the cognate receptor of these cytokines, suppressed the migration of macrophages co-cultured with highly metastatic cancer cells." (PMID 24924428, 2014). "Targeting of the IL-8 receptor CXCR2 has been suggested as a novel cancer treatment in several studies." (PMID 24321518, 2013). "The IL-8 chemokine activates multiple pathways following its engagement with two G protein receptors (CXCR1 and CXCR2), leading to the promotion of the proliferation, survival, and migration of cancer cells." (PMID 23632023, 2013). "CXCR2 is also highly expressed in certain other cancer cell types such as lung adenocarcinoma, laryngeal squamous cell carcinoma, endometrial carcinoma, rectal cancer, hepatocellular carcinoma and gastric cancer." (PMID 24376747, 2013). "To solidify the impact of NF-κB signaling on CXCR2-driven cancer progression, we employed CXCR2 shRNA to knockdown CXCR2 protein expression in SKCXCR2 cells and confirmed an inhibitory effect of CXCR2 shRNA." (PMID 24376747, 2013). "Through the G protein-coupled receptors CXCR1 and CXCR2, it exerts both inflammatory and angiogenic responses, and can directly stimulate cancer cell proliferation and survival." (PMID 22353811, 2012). "Consistently, in IHC analysis, a positive significant correlation was found exclusively between the scores of GLO1 and CXCL1 or CXCR2 in cancer tissues (Spearman's correlation coefficient = 0.238 and 0.293; P = 0.013 and P = 0.003, respectively)." (PMID 22479608, 2012). "Second, when the CXCR2-dependent senescence pathway is intact, it can restrict the growth and metastatic potential of hPTTG1-overexpressing cancer cells." (PMID 22789011, 2012). "Similar to hPTTG1, CXCR2 promotes malignant progression in certain types of cancer and triggers senescence in human normal fibroblasts." (PMID 22789011, 2012). "Among the cytokine related pathways, high expression of VEGF, CXCL8, CXCR2, and CXCL1 are associated with cancer metastasis and progression." (PMID 22479608, 2012). "The expression of IL-8 and the receptor of ELR+CXC chemokine CXCR2 in cancer have been evaluated in numerous studies." (PMID 20540789, 2010). "The intricate balance of CXCR2 signaling is vital for maintaining immune homeostasis, and dysregulation could lead to chronic inflammatory conditions and cancer progression." (PMID 41259376, 2025). "In addition, CXCL5 plays a vital role in the creation of pre-metastatic environments and is increased in metastatic lung tissue, directing the movement of cancer cells through the CXCL5/CXCR2 pathway." (PMID 39670859, 2025). "Moreover, previous research has demonstrated that CXCR2 is involved in promoting bone colonization and the metastasis of breast cancer tumor cells, closely linking it to cancer progression." (PMID 40079428, 2025). "Notably, PDAC exhibited a markedly higher proportion of myeloid cells compared with other cancer types, and CXCR2-positive cells (designated herein as CXCR2 TANs) were almost exclusively observed in PDAC." (PMID 41228323, 2025).